FMR1 (fragile X messenger ribonucleoprotein 1)
Diseases named in the same sentence as FMR1 in open-access papers (continued):
Sharing a sentence is not in itself a finding about the gene and the disease.
fragile X syndrome (continued). "The Fragile X Syndrome is usually caused by a triplet repeat expansion in the 5′UTR of the FMR1 gene leading to transcriptional silencing of the FMR1 mRNA and failure to produce the FMRP protein product." (PMID 20011099, 2009). "We introduced the I304N mutation into the endogenous Fmr1 locus to create a mouse model of Fragile X Syndrome." (PMID 20011099, 2009). "To address these issues, we have generated a new Fragile X Syndrome mouse model in which the endogenous Fmr1 gene harbors the I304N mutation." (PMID 20011099, 2009). "Fragile X Syndrome results from the hypermethylation of the Fmr1 promoter and loss of FMRP expression." (PMID 19015723, 2008). "Fragile X Syndrome (FXS) is associated with an unstable CGG repeat sequence in the 5’ untranslated region in the first exon of the FMR1 gene which resides at chromosome position Xq27.3 and is coincident with the fragile site FRAXA." (PMID 19440516, 2008). "Interpopulation variation in the polymorphism of the FMR1 gene and, consequently, in the predisposition to fragile X syndrome due to the prevalence of certain unstable alleles has been observed." (PMID 19440516, 2008). "However, some repeat loci, such as the CGG repeat in the FMR1 gene associated with Fragile X syndrome, exhibit extremely high GC content, making capture particularly difficult." (PMID 40921766, 2026). "This is of interest because of the reported dysregulation of innate immunity in Fragile X syndrome patients that have an impaired response to infectious diseases suggesting that innate immune cells may be disproportionately affected by Fmr1 deficiency." (PMID 41525319, 2026). "Similarly, CGG repeat alleles of the FMR1 gene in the intermediate/premutation range are much less prone to expansion into the pathogenic range, causing fragile X syndrome, when interrupted by one to four AGG units." (PMID 40624398, 2025). "To address this, we performed detailed characterization of two well-known triplet repeat loci: the CGG repeat in the 5' untranslated region (UTR) of FMR1, associated with Fragile X syndrome (FXS), and the CAG repeat in the coding region of HTT, associated with Huntington’s disease." (PMID 41256123, 2025). "Fragile X syndrome (FXS) is caused by the silencing of the FMR1 gene." (PMID 40901634, 2025). "While X chromosome inactivation reduces the impact of FXTAS in females, female premutation carriers face an increased risk of developing Fragile X-Associated Primary Ovarian Insufficiency (FXPOI) and of passing on a full FMR1 mutation, which can lead to Fragile X Syndrome (FXS) in their offspring." (PMID 40003975, 2025). "However, due the causal role in fragile x syndrome, most data are available about loss of FMR1 in neurons while functions of FXR1 and especially FXR2 remain largely unexplored." (PMID 41117937, 2025). "Fragile X syndrome is caused by an expanded CGG trinucleotide repeat in the fragile X messenger ribonucleoprotein 1 (FMR1) gene, leading to disrupted synaptic function and ASD-like behavioral phenotypes such as intellectual disability, hyperarousal, and impulsivity." (PMID 40605060, 2025). "In one study, dietary vitamin C shows therapeutic potential in Fragile X Syndrome (FX) by reducing DNA methylation at the X-linked Fragile X Messenger Ribonucleoprotein 1 (FMR1) gene locus, thereby restoring its expression in FX-induced pluripotent stem cells (iPSCs) and cerebral organoids." (PMID 40732992, 2025). "Fragile X syndrome (FXS) is a genetic disorder characterized by trinucleotide repeat expansions of the CGG sequence resulting in a mutation in the fragile X messenger ribonucleoprotein-1 (FMR1) located on the X chromosome." (PMID 40821284, 2025). "Methylation and transcriptional silencing of the Fragile X Messenger Ribonucleoprotein 1 (Fmr1) gene, due to the abnormal expansion of the trinucleotide CGG repeats in the promoter to over 200, leads to loss of encoded protein (FMRP), resulting in Fragile X syndrome (FXS)." (PMID 41469555, 2025).
fragile X syndrome (continued). "These 18 bb-CpGs were distributed across four different chromosomes, predominantly in the X chromosome and in the ASFMR1 (antisense FMR1) gene, which has been described as associated with clinical phenotypes of FMR1-related disorders such as X Fragile Syndrome." (PMID 39060467, 2024). "On BTA X, FMR1 has been associated with bull fertility traits and fragile X syndrome." (PMID 39682483, 2024). "The impact of being a female FMR1 premutation carrier is enormous, not only because it challenges women’s fertility and lifelong health, but also because it increases the risk of having and offspring with fragile X syndrome." (PMID 38760837, 2024). "Fragile X syndrome is caused by a deficiency in the fragile X mental retardation 1 protein (FMR1)." (PMID 38929088, 2024). "For example, fragile X Syndrome is a form of autism linked to epigenetic silencing in the promoter of the FMR1 gene; demethylation of its promoter could restore transcription, and this presumption has recently been clearly demonstrated." (PMID 37239005, 2023). "Fragile X Syndrome is the most known inherited form of intellectual disability due to an expansion in the full mutation range (>200 CGG repeats) of the promoter region of the FMR1 gene located on X chromosomes leading to gene silencing." (PMID 36831819, 2023). "For example, FMR1 has been identified as the pathogenic gene in fragile X syndrome." (PMID 37426677, 2023). "In contrast to these reports, the higher PAK1 S199/S204 phosphorylations are relevant to the seizure susceptibility in fragile X mental retardation 1 (Fmr1) KO mice (a Fragile X syndrome model), since FRAX486 (a PAKs inhibitor) reduces audiogenic seizure activity in this model." (PMID 37118736, 2023). "Fragile X syndrome (FXS) is a neurodevelopmental disorder due to mutations in the Fragile X messenger ribonucleoprotein 1 (FMR1) gene which prevent transcription of the Fragile X Messenger Ribonucleoprotein (FMRP)." (PMID 36641518, 2023). "Fragile-X syndrome is a developmental disorder that can be part of the autism spectrum, and previous studies have identified, in both humans and rodents, that the deficiency of the Fmr1 protein can be accompanied by an altered immune response." (PMID 37998759, 2023). "At the molecular level, in fragile X syndrome, the full mutation promotes DNA epigenetic changes leading to transcriptional silencing of the FMR1 promoter and thus, loss of expression of the FMR1-encoded protein, FMRP, ultimately resulting in autism and intellectual disability in male." (PMID 35295941, 2022). "The TNRC6 protein family, which includes, TNRC6C also has multiple reports in the literature of overlapping interactions with FMR1, the gene implicated in fragile X syndrome, which is one of the seven pathways prioritized in our analysis of the de novo variants." (PMID 35051175, 2022). "Among the best-known genetic risk factors for ASD, there are mutations causing the loss of the Fragile X Messenger Ribonucleoprotein 1 (FMRP) leading to Fragile X syndrome (FXS), a common form of inherited intellectual disability and the leading monogenic cause of ASD." (PMID 36581671, 2022). "Female carriers of the FMR1 premutation can pass the problematic gene to their children, which may cause fragile X syndrome, an inherited form of intellectual disability." (PMID 35026985, 2022). "Fragile X syndrome is one of the most common causes of X-linked intellectual disability and is caused by an expansion of a trinucleotide repeat region in the promoter of the FMR1 gene." (PMID 34773222, 2022). "This set of genes included cancer oncogenes (CMYC, CKIT, BCL2, KRAS) and genes associated with different cancer types (ADAM12, ALOX5, SRSF6, VEGF12) as well as FMR1, associated with fragile X syndrome (OMIM: 300624), and SNX12, which is associated with neurodegenerative diseases." (PMID 35573091, 2022). "The FMR1 gene is associated with fragile X syndrome in the offspring." (PMID 34361119, 2021).
fragile X syndrome (continued). "For example, prime editing could in theory be used to replace the hyperexpanded CGG repeat in FMR1 to treat Fragile X syndrome or rewrite large sections of SCN1A to treat multiple causes of DS." (PMID 32880951, 2021). "Over 200 CGG repeats in the 5′-UTR of FMR1 cause Fragile X syndrome (FXS), the most common inherited form of intellectual disability, due to transcriptional silencing induced by DNA methylation of the CGG trinucleotides and loss of the FMRP protein which has roles in synaptic plasticity." (PMID 33729487, 2021). "Fragile X syndrome (FXS) (OMIM #300624) is a rare neurodevelopmental disorder caused by a trinucleotide (CGG) repeat expansion mutation in the promoter region of the fragile X mental retardation gene (FMR1, located at Xq27.3)." (PMID 34625026, 2021). "Fragile X syndrome (FXS) is an X-linked disorder due to a loss of FMR1 function." (PMID 34828275, 2021). "Additional testing discussed in this review can aid in detection of some variants that CMA is unable to detect, including FMR1 CGG repeat analysis for the trinucleotide repeat expansion that causes fragile X syndrome and ES for detection of exonic sequence variants." (PMID 33681094, 2021). "The 5’ untranslated region of the FMR1 gene contains a CGG repeat that is responsible for at least three distinct clinical phenotypes: fragile X syndrome (FXS), fragile X–associated tremor/ataxia syndrome (FXTAS), and fragile X–associated primary ovarian insufficiency (FXPOI)." (PMID 33927378, 2021). "Loss of FMR1 expression is responsible for Fragile X syndrome, the most common form of XLID." (PMID 34388204, 2021). "Development of Fragile X Syndrome (FXS) or the related disease Fragile X-associated Tremor/Ataxia Syndrome (FXTAS) is caused by the presence of a triple CGG repeat motif in the 5′ untranslated region (5′-UTR) of the FMR1 gene." (PMID 34349622, 2021). "Fragile X syndrome (FXS) is an ASD caused by insufficient expression of the FMR1 gene." (PMID 32660622, 2020). "Female FMR1 premutation carriers must be counseled about the high risk of having an affected male child with the physical and behavioral features of Fragile X syndrome, and about the available methods for preventing its occurrence, such as preimplantation genetic testing." (PMID 32155011, 2020). "The associations described between the condition and a few noteworthy genetic diseases - fragile X syndrome (mutation in the FMR-1 gene on X chromosome at Xq27), chromosome X trisomy (47, XXX), and Turner’s syndrome (monosomy of chromosome X; 45,X0), to name a few - are still controversial." (PMID 32293822, 2020). "Importantly, in a mouse model of fragile X syndrome, Fmr1 KO mice, a common disease associated with dysregulation of synaptic protein synthesis, we observed altered morphology and respiration rates of synaptic mitochondria." (PMID 32558077, 2020). "Moreover, fragile X syndrome, which results from mutations in the fragile X mental retardation 1 (FMR1) gene, has been considered the most prevalent cause of monogenic ASD." (PMID 32659996, 2020). "The cause of fragile X syndrome (FXS) is a lack or deficiency of the FMR1 protein (FMRP)." (PMID 32576818, 2020). "Fragile X Syndrome is associated with Cytosine-Guanine-Guanine (CGG) repeat sequence expansion located in the 5′ untranslated region (UTR) in the Fragile X Mental Retardation gene 1 (FMR1), at the Xq27 position." (PMID 32012997, 2020). "Fragile X syndrome Fragile X syndrome is an autosomal dominant genetic disorder caused by the presence of over 200 repetitions of the CGG triplet sequence in the FMR1 (Fragile X Mental Retardation 1) gene or by a deletion affecting the FMR2 (Fragile X Mental Retardation 2) gene." (PMID 31412890, 2019). "Fragile X syndrome (FXS) is a neurodevelopmental condition that is caused by the expansion of the CGG repeat in the 5′ untranslated region of fragile X mental retardation 1 (FMR1) gene located on the X chromosome." (PMID 30678024, 2019).
fragile X syndrome (continued). "Fmr1 encodes an RNA-binding protein, which acts as a neural growth brake regulating RNA trafficking, translation and neuronal excitability, and whose downregulation contributes to Fragile X syndrome in humans." (PMID 30530644, 2019). "Residing on the long arm of the X chromosome, FMR1 in its full mutation state (CGG repeats >200) results in fragile X syndrome (FXS), which is the most common heritable cause of intellectual disability and the leading known genetic cause of autism spectrum disorder (ASD)." (PMID 31348790, 2019). "In addition, we showed that Fragile X Mental Retardation gene 1 (Fmr1), which is mutated in the autism spectrum disorder fragile X syndrome, is an important regulatory target for miR-129-5p." (PMID 30911036, 2019). "Nevertheless, this strategy may not be optimal, as inactivation of the FMR1 mRNA may aggravate disease because fragile X syndrome is caused by loss of FMRP." (PMID 31098852, 2019). "Furthermore, in addition to the genetic defect in Tsc1/2 and Pten, the lack of FMR1 expression, which leads to fragile X syndrome (FXS), an autism-associated disorder, also demonstrated hyperactive mTOR signaling both in KO mice and in FXS patients." (PMID 31849609, 2019). "Loss of FMR1 protein (FMRP) results in fragile X syndrome (FXS) - a common single gene cause of ID." (PMID 31653898, 2019). "Fragile X syndrome (FXS) is mostly caused by two distinct events that occur in the FMR1 gene (Xq27.3): an expansion above 200 repeats of a CGG triplet located in the 5′UTR of the gene, and methylation of the cytosines located in the CpG islands upstream of the CGG repeats." (PMID 30450110, 2018). "Additionally, some genetic epilepsies are at high risk of ASD, such as tuberous sclerosis/TSC2 gene and Fragile X syndrome/FMR1 gene." (PMID 29558884, 2018). "Fragile X syndrome (FXS) is caused by transcriptional silencing of the FMR1 gene during embryonic development with the consequent loss of the encoded fragile X mental retardation protein (FMRP)." (PMID 30072797, 2018). "Some structure specificities increase the possibility of the disruption of the structures within binding sites, which might cause diseases, e.g. protein FMR1 in fragile X syndrome." (PMID 29970003, 2018). "Mutations in Fmr1 gene are linked to human fragile X syndrome and autism." (PMID 30087606, 2018). "Fragile X syndrome (FXS) is caused by an unstable expansion of a polymorphic trinucleotide (CGG) repeat sequence in the regulatory region of the fragile X mental retardation 1 gene (FMR1), which leads to its epigenetic silencing via atypical methylation." (PMID 28616097, 2017). "Additionally, 3′UTR mutation in FMR1 has been shown to cause fragile X syndrome by disrupting the mRNA binding protein HuR, leading to destabilization and rapid degradation of the FMR1 transcript." (PMID 28754144, 2017). "Additionally, some important repeats, like the repeat in FMR1 gene that causes fragile X syndrome, are 100% GC and are underrepresented in sequence data that includes a PCR step during sample preparation." (PMID 28887402, 2017). "Fmr1 mutations lead to a developmental condition called Fragile X Syndrome (FXS)." (PMID 28880200, 2017). "Interestingly, people with Fragile X syndrome often exhibit autistic behaviors and mutations of FMR1 genes are also found in several cases of ASD." (PMID 27909399, 2016). "Fragile X syndrome is caused by the silencing of the FMR1 (Fragile X Mental Retardation 1) gene." (PMID 26188466, 2016). "Therefore, accurate quantification of FMR1 mRNA levels is of importance for studies of both fragile X syndrome and of other Fragile X-associated Disorders in PM and FM individuals." (PMID 27387142, 2016).
fragile X syndrome (continued). "Similarly, miR-34a, 34b, and 34c are upregulated in the hippocampus of Fmr1 KO mice: a CGG trinucleotide repeat in the FMR1 gene causes Fragile X syndrome." (PMID 26173148, 2015). "These alterations to gene expression regulation in the developing neocortical circuit may also contribute to cognitive dysfunctions in X fragile syndrome caused by mutations in FMRP coding gene FMR1." (PMID 26321900, 2015). "Loss of expression of FMR1 is associated with Fragile X syndrome." (PMID 24714572, 2014). "In a recent case of an application for the treatment of Fragile-X syndrome which discussed in 2013, the sponsor presented data in a preclinical model of the condition using FMR1 deficient mice, as well as preliminary clinical data in patients affected by the condition." (PMID 25475155, 2014). "Expansions of more than 200 CGG repeats (full mutation) in the FMR1 gene give rise to fragile X syndrome (FXS) through a process that generally involves hypermethylation of the FMR1 promoter region and gene silencing, resulting in absence of expression of the encoded protein, FMRP." (PMID 25278957, 2014). "Interestingly, the levels of FMR1 mRNA are 5- to 10-fold higher in fragile X syndrome pre-mutation carriers with >55–200 repeats than in normal subjects." (PMID 25268620, 2014). "However, in contrast to these previous reports, our patient had preferential inactivation of the deleted X-chromosome and a normal sized and unmethylated FMR1 allele, and the diagnosis of Fragile X syndrome was also excluded." (PMID 23634718, 2013). "The FMR1 gene codes for the production of the fragile X mental retardation protein known to be involved in cognitive development, and mutations of this gene result in fragile X syndrome." (PMID 23717269, 2013). "Identification of other mutations (e.g., deletions in patients with the typical phenotype) has confirmed that FMR1 is the only gene involved in the pathogenesis of fragile X syndrome, and the loss of the FMR1 product, fragile X mental retardation protein (FMRP), causes fragile X syndrome." (PMID 22655085, 2012). "Fragile X syndrome (FXS) is the most common inherited cause of intellectual disability due to an expansion in the full mutation range (>200 CGG repeats) of the promoter region of the FMR1 gene leading to gene silencing." (PMID 23074686, 2012). "Fragile X syndrome (FXS) is caused by loss of function mutations in the FMR1 gene." (PMID 20221430, 2010). "Taken together, given the degree of similarity in the phenotypes between Fmr1I304N and Fmr1 null mice, including their behavior, macroorchidism and altered synaptic plasticity, we conclude that the I304N mutation in FMRP is sufficient to cause symptoms of the Fragile X Syndrome." (PMID 20011099, 2009). "The Fmr1I304N mice display the same degree of macroorchidism as their null counterparts, and this increases with age, as in the Fmr1 null mice and in the human patients, supporting the conclusion that the Fmr1I304N mutation is sufficient to phenocopy the Fragile X Syndrome." (PMID 20011099, 2009). "Fragile X Syndrome is caused by the silencing of the Fragile X Mental Retardation gene (FMR1)." (PMID 19888420, 2009). "In nearly all cases, the Fragile X Syndrome is caused by transcriptional silencing of the fragile X mental retardation 1 (FMR1) gene as a result of CGG repeat expansion and hypermethylation of CpG islands in the 5′UTR region, culminating in loss of FMRP expression." (PMID 20011099, 2009). "The cellular physiology and the cortical patterns of expression of the protein associated with FMR1 have been recently mapped out, making fragile X syndrome a unique model to investigate the relationships between the silencing of a single gene and the development of neurocognitive dysfunction." (PMID 17254617, 2007).